SMARCA4 (SWI/SNF related BAF chromatin remodeling complex subunit ATPase 4)
Diseases named in the same sentence as SMARCA4 in open-access papers (continued):
Sharing a sentence is not in itself a finding about the gene and the disease.
tumor (continued). "Previous studies have identified specific mutation types associated with tumor sensitivity to AURKA inhibitors, such as RB1 deficiency or loss of SMARCA4 or ARID1A." (PMID 38521813, 2024). "A left upper lobectomy and lymphadenectomy were performed, and postoperative pathology confirmed that the tumor was Thoracic SMARCA4-UT." (PMID 39723373, 2024). "Several of the SCLC-Y tumor lines showed close transcriptional similarities with primary thoracic SMARCA4-UT." (PMID 38180245, 2024). "Although SMARCA4 is a tumor suppressor, it has been shown that SMARCA4 expression is upregulated in cancer compared to healthy tissues." (PMID 39697230, 2024). "SMARCA4/2 inhibition with FHD-286 monotherapy slightly decreased tumor growth in all models tested; in contrast, the combination of FHD-286 with afatinib induced strong growth-suppressive responses in all models assessed." (PMID 39080761, 2024). "This influences essential cellular processes such as differentiation and cell cycle regulation, and SMARCA4 is widely regarded as a tumor suppressor." (PMID 39492586, 2024). "SMARCA4 showed partial mosaic inactivation, particularly in the anaplastic areas of the tumor located at the invasion front." (PMID 39590317, 2024). "There is also a macroscopic difference due to tumor size, which is significantly larger for SMARCA4-UT." (PMID 38542211, 2024). "Thoracic SMARCA4-dUT is a new type of devastating neoplasm, and most cases of SMARCA4-dUT exhibit an advanced stage at presentation with considerably poor survival outcomes." (PMID 38881888, 2024). "Our findings demonstrate that, in contrast to SCLC, both xenografts of SMARCA4-mutant cell lines previously classified as SCLC-Y and patient-derived primary SMARCA4-UT tumor samples show diffuse, uniformly strong YAP1 protein staining." (PMID 38180245, 2024). "SMARCA4, also known as BRG1, encodes a core component of this complex and is recognized as a tumor suppressor gene." (PMID 38610978, 2024). "Consistent with the high YAP1 mRNA expression seen in SCLC-Y cell lines, strong YAP1 protein expression was observed in all tumor cell lines within the SMARCA4-UT cluster and NSCLC cluster." (PMID 38180245, 2024). "Upon further investigation into the correlation between baseline tumor tissue-NGS and immunotherapy prognosis, we identified a significant association between SMARCA4 mutation status and both PFS and OS." (PMID 38890392, 2024). "SMARCA4 is involved in various biological normal and tumor tissue processes through its ability to regulate gene activity." (PMID 39697230, 2024). "Among the patients with SMARCA4-dNSCLC, 98.1% were male, 85.7% were smokers, and 79.5% (35/44) had tumor-node-metas­tasis (TNM) III-IV tumors." (PMID 38374950, 2024). "SMARCA4-dUT of the thorax is a rare but aggressive neoplasm primarily occurring in heavy-smoking adults aged 30–59 years." (PMID 38881888, 2024). "Histologically, a solid architecture, irregular sheet or nest arrangement, typical infiltration of the surrounding tissues, typical tumor necrosis, and rhabdoid morphology were the major pathological characteristics of thoracic SMARCA4-DTs." (PMID 38374950, 2024). "Among them, some transcription factors have been reported to mediate the EMT process, such as TBL1XR1, STAT6, ETV6, and SMARCA4, indicating their potential to regulate VM and promote tumor invasion." (PMID 38694917, 2024). "Staining with Brahma-related gene-1 (BRG1), the SMARCA4 protein product, demonstrated loss of expression within tumor cells with intact staining in adjacent stromal cells." (PMID 38497146, 2024). "Here, we shed light on the origins of the proposed controversial “SCLC-Y” subtype, making the surprising observation that the majority of SCLC-Y tumor cell lines, on which the classification of SCLC-Y category was largely based, harbour SMARCA4 mutations." (PMID 38180245, 2024).
tumor (continued). "In SMARCA4-deficient NSCLC, tumor cells display differentiated epithelial structures and strong expression of epithelial markers, whereas in SMARCA4-UT, tumor cells are poorly differentiated with scattered weak or negative expression of epithelial markers." (PMID 38903719, 2024). "Immunostaining revealed that BRG1 (SMARCA4) expression was lost in the tumor cells, whereas INI1 (SMARCB1) and BRM (SMARCA2) proteins were retained." (PMID 38923369, 2024). "Due to its non-specific histologic appearance and variable staining in expanded immunohistochemical panels, this tumor frequently overlaps with other tumor types, making the diagnosis of SMARCA4-UT challenging." (PMID 38497146, 2024). "In cancer, both SMARCA2 and SMARCA4 have emerged as critical tumor suppressors, although several reports unveil their oncogenic potential." (PMID 36674511, 2023). "Multiple pan-cancer studies have documented SMARCA4 genetic alterations from human tumour sequencing data, with a wide variety of aberrations observed." (PMID 37433987, 2023). "To further determine the therapeutic benefits of GSK-PTi and BBAi-1 in vivo, we established SMARCA4-WT or -R1157W mutant HCT116 cell line-derived xenograft (CDX) tumor models." (PMID 36922568, 2023). "As an oncogene, several studies have shown that SMARCA4 promotes the occurrence and development of tumors by promoting the invasion and metastasis of tumor cells through the process of EMT." (PMID 36902184, 2023). "Further mechanistic studies showed that the miR-199a-5p regulated SMARCA4 can promote the invasion and metastasis of tumor cells through EMT." (PMID 36902184, 2023). "Previous studies have shown that overexpression of SMARCA4 is involved in the development of various tumors by promoting tumor cell invasion and motility." (PMID 36902184, 2023). "Some patients with SMARCA4-UT responded to ipilimumab and pembrolizumab during immunotherapy, and nivolumab also showed tumor regression in some patients with SMARCA4-UT." (PMID 37115343, 2023). "Most patients with SMARCA4‐dNSCLC had stage IV disease at diagnosis, with large aggressive tumors, high tumor proliferation indices (Ki‐67), more adrenal metastases, and more lymph node metastases." (PMID 37184108, 2023). "Comparatively, SMARCA4 mutation is rarely seen in the SHH subgroup of MB and is a crucial regulator of underlying epigenetic networks of this tumour type which are required for tumourigenesis." (PMID 37433987, 2023). "Previous studies have revealed that SMARCA4 plays a tumor-suppressive or oncogenic role in a context-dependent manner in various cancers." (PMID 36902184, 2023). "SMARCA4 acts as a tumor suppressor and, being downregulated, promotes colorectal cancer metastasis via this axis." (PMID 37175555, 2023). "Loss of SMARCA4 also leads to downregulation of CD1, limits CDK4/6 activity in tumor cells, and affects sensitivity to CDK4/6 inhibitors." (PMID 37115343, 2023). "An important role of altered SMARCA4 in MB development was suspected before since the overexpression of SMARCA4 wild-type represses tumor development in an OTX2/MYC Group 3 MB mouse model." (PMID 37919824, 2023). "It is noteworthy that both tumor types can focally express neuroendocrine markers (synaptophysin, chromogranin, and INSM1) in most SMARCA4-deficient carcinomas and up to 18% of SMARCB1-deficient carcinomas." (PMID 36941503, 2023). "The presence of recombined Smarca4 in tumor biopsies was also verified by PCR, which confirmed that the loss of SMARCA4 was caused by genetic recombination." (PMID 37919824, 2023). "SMARCA4 mutations observed in ATRT are commonly homozygous and inactivating, which is characteristic of a tumour suppressor gene." (PMID 37433987, 2023). "This is likely due to the fact that SMARCA4 is reported to have a tumour suppressing role in ATRT, whereas it is known to be an oncogenic driver in SHH-group MB." (PMID 37433987, 2023).
tumor (continued). "Of note, tumor cells in 12 cases (80%) with SMARCA4‐UTs expressed vimentin, whereas only 5 cases (41.7%) with SMARCA4‐NSCLCs were positive for vimentin." (PMID 38124509, 2023). "The group with score 3, which showed higher expression of SMARCA4 in whole tumor tissue than in normal hepatocytes, had a significantly poorer prognosis than the group with score 1 and score 2 (p < 0.001)." (PMID 37626774, 2023). "In most SMARCA4‐UT cases, tumor cells typically appeared as monomorphic, undifferentiated round or oval cells with large nuclei and occasionally prominent nucleoli, exhibiting discohesive arrangement." (PMID 38124509, 2023). "Tumor cells were diffusely positive for Synaptophysin, CD56, INI1 and SMARCA4 associated with negativity for GFAP, OLIG-2, EMA, BCOR, LIN28A and MIC-2." (PMID 36934287, 2023). "Despite this discrepancy, SMARCA4 appears to have a classic tumour supressing role in both subgroups due to the significant occurrence of characteristic inactivating point mutations associated with cancer development." (PMID 37433987, 2023). "Each primary tumor and related recurrence had the same mutations in SMARCB1 or SMARCA4 and genotype matching confirmed that they belonged to one patient based on the identification of common SNPs." (PMID 37450044, 2023). "In agreement with a potential role of chromatin remodeling in the prevention TRC-dependent DNA damage, SMARCA4-, SMARCA5- and INO80-deficient tumor samples display significantly increased R-loop mutation burden." (PMID 37898641, 2023). "We report two cases of advanced SMARCA4-deficient NSCLC treated with ICIs, in which marked regression of the tumor and improved general condition of the patients were achieved." (PMID 37200668, 2023). "One study profiled 192 ATRT tumours and identified 3 tumours that showed retained SMARCB1 expression, with all 3 of these tumours carrying a mutation in SMARCA4 and clustering in the SHH-subgroup of ATRT." (PMID 37433987, 2023). "This tumor has been characterized by inactivation of SMARCB1 or rarely SMARCA4, which encodes hSNF5/BAF47/INI1 and BRG1, respectively." (PMID 38124207, 2023). "SMARCA4‐NSCLC tumor cells were more cohesive, displaying from mild to moderate pleomorphism and clear or pale eosinophilic cytoplasm." (PMID 38124509, 2023). "Consistent with this, proximity ligation and co-immunoprecipitation showed FOXA1 interacting with both SMARCD3 and SMARCA4 in KPf/fC tumor cells; this interaction was enriched in primary KPf/fC stem cells." (PMID 36653361, 2023). "Tumor cells were diffusely positive for Synaptophysin, CD56, INI1, SMARCA4 and ATRX associated with negativity for GFAP, OLIG-2, EMA, BCOR, LIN28A, EZHIP, MIC-2, Cytokeratin’s, SMA, Desmin and Myogenin." (PMID 36934287, 2023). "To further elucidate the tumorigenesis effect of SMARCA4 on OSCC in vivo, we examined the effect of SMARCA4 inhibition on tumor growth using a xenografts model in nude mice." (PMID 36902184, 2023). "Whole-exome sequencing revealed 99 somatic mutations including SMARCA4, ARID2, TET2, CDKN2A, WNT7A, NOTCH3 and STAG2, all present both in the primary tumor and in the cell line." (PMID 38201285, 2023). "Different from the original primary tumor, cell line TCS627 demonstrated loss of SMARCA4 and SMARCA2 in a very large majority of cells, while SMARCB1 expression was completely absent." (PMID 38201285, 2023). "SMARCA4-UT histologically resembles SMARCB1 (INI1)-deficient tumors, showing a highly rhabdoid appearance and frequent cytokeratin expression in tumor cells." (PMID 37115343, 2023). "Even epigenetic changes are involved in this tumor biology, such as key mutations in chromatin remodeling (MERC1, SMARCA2, ARID1A, ARID1B, SMARCA4) and an imbalance in miRNAs (miR-155, miR-320a, miR-99a, miR-205) that regulate gene expression." (PMID 37476370, 2023). "Most of the examined cases showed a diffusely distributed expression pattern of different staining intensities within the same tumor for both SMARCA4 and SMARCE1." (PMID 36916408, 2023).
tumor (continued). "SMARCA4-UT is an aggressive tumor that metastasizes rapidly; therefore, early diagnosis is critical for prognosis." (PMID 37115343, 2023). "The third patient with a SCCOHT tumor phenotype (patient #3) showed a biallelic somatic SMARCA4 inactivation (see supplement for detailed medical cancer history of all three SCCOHT families, including genetic test results)." (PMID 37345881, 2023). "These different tumor types display highly variable immunophenotypes with SMARCB1-deficient carcinomas showing variable squamous immunophenotype, while their SMARCA4-related counterparts lack such features altogether." (PMID 35307773, 2022). "These regions contained tumor-related genes, such as Muc16, Pik3, and Bcl2 in amplification regions and Hras, Notch1, Apc2, Ccnd1, Batf2, Dapk3, Smarca4, Traf2, Traf3, Cdk3, and Cdh4 in deletion regions." (PMID 36424557, 2022). "Numerous mutated genes correlated with tumor therapy response, such as EGFR, KRAS, ARID1A, and SMARCA4." (PMID 36290859, 2022). "SMARCA4 is generally overexpressed in multiple cancer types compared to the non‐tumour control and the predicted unfavourable outcome in the GEO database (GSE65904)." (PMID 36317703, 2022). "In multivariable analysis for disease-specific survival, any alteration in SMARCA4 (DSS; HR 3.911, 95%CI 1.561–9.795, P=0.004) exhibited independent prognostic significance along with stage, tumor mutation burden, and predominant histological subtypes." (PMID 35964518, 2022). "About 85% of our B-SqCC cases had diffuse (> 70%) CK5/6 positivity which would be unusual in SMARCA4-deificient tumor." (PMID 35538551, 2022). "Tazemetostat, an EZH2 inhibitor, is currently under evaluation in different Phase I and II clinical trials in tumours with SMARCB1, SMARCA4 and EZH2 mutations with positive results in patients with different solid tumours." (PMID 36138075, 2022). "Analyses of genetic alterations in SMARCB1/SMARCA4 were available for 83% (83/100) of patients (tumor and/or blood)." (PMID 35565313, 2022). "The potential roles of SMARCA4 in different tumors were explored based on The Cancer Genome Atlas (TCGA), Genotype-tissue expression (GTEx), Tumor Immune Estimation Resource (TIMER), and Gene Set Enrichment Analysis (GSEA) datasets." (PMID 34675941, 2021). "We identified nonsynonymous SNVs in tumor tissues, such as SMARCA4 (in 192D0360T and 192D0641T), BCOR and LRP1B in 192D0641T, as well as frameshift mutations of KMT2D in 192D0695T and truncating mutations of PTCH1 in 192D0583T." (PMID 33707557, 2021). "The expression level of SMARCA4 in tumor tissues was significantly lower than control tissues of kidney renal clear cell carcinoma (KIRC, p< 0.001) and kidney chromophobe (KICH, p< 0.05)." (PMID 34675941, 2021). "Their frequency and poor prognosis mean that the use of GSK-J4 or similar compounds can have a great impact on the treatment of SMARCA4-mutant tumours." (PMID 34262032, 2021). "Mutation and deletion of BRG1/SMARCA4 have been shown to contribute to a range of human malignancies, suggesting that the SWI/SNF complex acts as a tumor suppressor in these cancers." (PMID 34577604, 2021). "Our investigation of SMARCA4 revealed that BRG1 is over-expressed in the majority of the 486 tumours from The Cancer Genome Atlas prostate cohort, as well as in a complementary panel of 21 prostate cell lines." (PMID 33596994, 2021). "Elevated SMARCA4 gene expression is detrimental to survival in some situations with contradictory results in other tumor types." (PMID 34675941, 2021). "The genetic alteration status of SMARCA4 in different tumor samples of the TCGA cohorts were analyzed." (PMID 34675941, 2021).
tumor (continued). "A large area of research in SMARCA4-dNSCLC tumor treatment is being dedicated towards tumor suppressor activity of bromodomain and extra-terminal motif protein inhibitors (BETi) across several cancer types." (PMID 34440689, 2021). "Together, these results from multiple cohorts of cell lines and patient tumor samples support the cooperative roles of SMARCA4/2 in regulating ITPR3 and confirm reduced IP3R3 expression in SMARCA4/2-deficient cancers." (PMID 34518526, 2021). "Mutations in ARID1A, ARID2, BRAF, SMARCA4, TERT and IDH1 were significantly exclusive to intracranial metastases while the same variants remained undetected in the corresponding extracranial tumor tissues." (PMID 33578810, 2021). "Microarray analysis of the somatic tumor tissue revealed a 21.185 kbp loss of heterozygosity (LOH) within the 19p12-p13.3 region (260912_22445808), which encompasses 692 genes including SMARCA4." (PMID 33907931, 2021). "The study cohort consisted of 56 SWI/SNF‐deficient DDEC/UEC (2 POLE‐mutated), which showed either SMARCA4 (BRG1) loss, ARID1A/1B co‐loss, or SMARCB1 (INI1) loss in the undifferentiated tumor, and 26 SWI/SNF‐intact DDEC/UEC (4 POLE‐mutated)." (PMID 33125840, 2021). "As expected, SMARCA4 expression levels were reduced, whereas SMARCB1 expression levels were higher in SMARCA4-deficient tumor samples compared to all other ATRT subgroups (online resource)." (PMID 33331994, 2021). "The majority of DDEC/UEC harbor inactivating mutations involving core components of SWI/SNF complex with SMARCA4 and ARID1A/ARID1B being most commonly inactivated, resulting in absent expression of corresponding proteins in the undifferentiated tumor." (PMID 33125840, 2021). "In typical cases, SMARCA4-DTSs is a poorly differentiated neoplasm of round to epithelioid cells with prominent cytological atypia organized in a solid pattern and showing rhabdoïd differentiation." (PMID 33866513, 2021). "Upon tumor establishment, we induced SMARCA4 expression with doxycycline treatment, which indeed resulted in suppression of tumor growth." (PMID 34518526, 2021). "Since SCCOHT has been studied longer than SMARCA4–dNSCLC, potential treatment strategies have been worked out to create a paradigm shift in the epigenetic dysregulation of the prior tumor." (PMID 34440689, 2021). "In the same way, other teams also demonstrated that SMARCA4 loss was a useful tools to differentiate SCCOHT from histologic mimics and rare tumours of young women." (PMID 31844183, 2020). "In the one SMARCA4 wild-type tumor (IGR-03) which showed concomitant ARID1A and ARID1B mutations, SMARCA2 expression was higher at the mRNA level (real-time RT-PCR) than in SMARCA4 mutated samples, and interpreted as ambiguous/low at the protein level (IHC)." (PMID 32575483, 2020). "Whole-exome sequencing (WES) was performed on a single tumour with retained SMARCA4/SMARCA2 expression (ID 23)." (PMID 31844183, 2020). "SMARCA4 is an ATPase subunit essential for the SWI/SNF chromatin remodeling complex in mammals and is also involved in expression of the tumor-suppressor gene SNF2β." (PMID 32708644, 2020). "The genes encoding the ATPase of the chromatin remodeling SW1/SNF complexes SMARCA4 and the alternative SMARCA2 are usually mutated or silenced in tumors, suggesting a role as tumor suppressor." (PMID 33218162, 2020). "The ability of SMARCA2 to compensate for the loss of SMARCA4 has made SMARCA2 an attractive therapeutic target for SMARCA4-mutant tumor types, motivating multiple groups to generate SMARCA2 small molecule inhibitors or degraders." (PMID 33144586, 2020). "It was also discovered that tumor-suppressor and oncogenic mutant BAF complexes have different effects on PRC eviction and disease-associated mutations in Smarca4 (or BRG1, the ATPase of the BAF complex) disrupt the eviction of PRC1." (PMID 32028669, 2020).